CACNG6 (calcium voltage-gated channel auxiliary subunit gamma 6)
Description:
Regulates the activity of L-type calcium channels that contain CACNA1C as pore-forming subunit.
Tractability: Small molecule: an approved drug acts on it; a high-quality ligand is known; it belongs to a druggable protein family. Antibody: UniProt places it where antibodies can reach, with high confidence; its Gene Ontology location is reachable by antibodies, with high confidence; UniProt predicts a signal peptide or a membrane-spanning region.
Gene: Protein-coding gene on chromosome 19 (53,991,637 to 54,012,666, forward strand). Ensembl gene ENSG00000130433.
Subcellular location: Cell membrane
Subcellular location (Human Protein Atlas): Nucleoli fibrillar center; Cytosol
Pathways (Reactome):
Muscle contraction: Phase 0 - rapid depolarisation; Phase 2 - plateau phase
Gene Ontology:
Molecular function: calcium channel regulator activity; voltage-gated calcium channel activity
Biological process: calcium ion transport; regulation of calcium ion transmembrane transport via high voltage-gated calcium channel; calcium ion transmembrane transport
Cellular component: L-type voltage-gated calcium channel complex; plasma membrane; voltage-gated calcium channel complex; membrane
Genetic constraint (gnomAD): Loss-of-function variants: 21 observed, 18.81 expected, observed/expected ratio (o/e) 1.12, 90% interval 0.79 to 1.6. The synonymous counts are far from expectation, so gnomAD's model fits this gene poorly and the ratio says little. Missense variants: 326 observed, 271.99 expected, observed/expected ratio (o/e) 1.2, 90% interval 1.09 to 1.31. Synonymous variants: 176 observed, 127.36 expected, observed/expected ratio (o/e) 1.38, 90% interval 1.22 to 1.57.
Homologues: Orthologues: chimpanzee CACNG6 (99% identical), macaque CACNG6 (97% identical), dog CACNG6 (89% identical), pig CACNG6 (89% identical), rat Cacng6 (86% identical), mouse Cacng6 (85% identical), guinea pig CACNG6 (85% identical), rabbit CACNG6 (84% identical), zebrafish cacng6b (46% identical), zebrafish cacng6a (44% identical). Paralogues in human: CACNG1 (33% identical).
Diseases named in the same sentence as CACNG6 in open-access papers:
CACNG6 is named in the same sentence as 9 diseases in open-access papers, as found by Europe PMC text mining. Sharing a sentence is not in itself a finding about the gene and the disease. The quoted sentences say what the papers report.
asthma (1 paper, 2010). "Since the role of azelastine in asthma treatment is achieved by blocking the L-type calcium channel thus, preventing Ca(2+) current, the CACNG6 may, therefore, be of interest in the study of asthma treatment." (PMID 20860846, 2010). "When comparing LDs on 8 SNPs of CACNG6 among Korean asthmatic patients and other populations, albeit non-asthmatic Korean population has not determined, it can be assumed that a different LD status of the asthmatics may affect AIA and/or asthma-related phenotypes at least in a Korean population." (PMID 20860846, 2010).
breast carcinoma (1 paper, 2025). "Although the role of CACNG6 is poorly understood, other members of the TARP family, such as CACNG2, have been linked to chronic pain conditions, including post-mastectomy pain in breast cancer patients and neuropathic pain." (PMID 40577278, 2025).
chronic obstructive pulmonary disease (1 paper, 2010). A chronic and progressive lung disorder characterized by the loss of elasticity of the bronchial tree and the air sacs, destruction of the air sacs wall, thickening of the bronchial wall, and mucous accumulation in the bronchial tree. "On the other hand, previous studies have reported that concentration of calcium ion is related with leukotriene secretion and that CACNG6 gene is negatively expressed in chronic obstructive pulmonary disease and human airway epithelium following injury." (PMID 20860846, 2010). "Recent studies have revealed negative relations of CACNG6 gene expression to chronic obstructive pulmonary disease, responses of the human airway epithelium following injury and % parenchyma in lung tissues." (PMID 20860846, 2010).
schizophrenia (1 paper, 2016). A major psychotic disorder characterized by abnormalities in the perception or expression of reality. "Of note, the current microarray data identified four gamma subunits of the L-type voltage-gated calcium channels to be down-regulated in PCP-SI rats, and single nucleotide polymorphisms in two of these (CACNG4 and CACNG6) have recently also been associated with schizophrenia." (PMID 27382048, 2016).
cancer (2 papers, 2017 to 2025). A tumor composed of atypical neoplastic, often pleomorphic cells that invade other tissues. "Our results showed that genes CACNG6, DUSP6 and MAP4K3 in the MAPK pathway have reorganized spatial structures in MM, and associate with gene expression regulation as well as epigenetic mark changes, which might contribute to cancer development." (PMID 29203764, 2017). "Despite these mechanistic insights, our study is the first to implicate LILRA6, CACNG6, and PRSS33 in cancer-related symptoms." (PMID 40577278, 2025).
CACNG6 also shares sentences with these, for which no sentence is quoted: dilated cardiomyopathy (2 papers); hypertrophic cardiomyopathy (2); arrhythmogenic right ventricular cardiomyopathy (1); childhood asthma (1).